SLC25A45 (solute carrier family 25 member 45)
Description:
Mitochondrial transporter that specifically mediates the mitochondrial uptake of dimethylarginine and trimethyllysine amino acids, and which is required for carnitine biosynthesis. Involved in carnitine biosynthesis by mediating the mitochondrial import of trimethyllysine, a precursor for carnitine biosynthesis. Transports both symmetric and asymmetric dimethylarginine. Does not transport unmethylated arginine and lysine.
Tractability: Antibody: UniProt predicts a signal peptide or a membrane-spanning region.
Gene: Protein-coding gene on chromosome 11 (65,375,192 to 65,384,550, reverse strand). Ensembl gene ENSG00000162241.
Subcellular location: Mitochondrion inner membrane
Subcellular location (Human Protein Atlas): Cytosol
Gene Ontology:
Biological process: amino acid transmembrane transport; carnitine biosynthetic process; L-alpha-amino acid transmembrane transport; transmembrane transport
Cellular component: mitochondrial inner membrane; mitochondrion
Genetic constraint (gnomAD): Loss-of-function variants: 27 observed, 30.47 expected, observed/expected ratio (o/e) 0.89, 90% interval 0.65 to 1.22. The upper end of that interval is the gene's LOEUF score, 1.22, which puts it in group 5 of 6, group 1 being the genes least tolerant of losing a copy. Missense variants: 355 observed, 400.85 expected, observed/expected ratio (o/e) 0.89, 90% interval 0.81 to 0.97. Synonymous variants: 136 observed, 163.38 expected, observed/expected ratio (o/e) 0.83, 90% interval 0.72 to 0.96.
Homologues: Orthologues: chimpanzee SLC25A45 (99% identical), pig SLC25A45 (90% identical), mouse Slc25a45 (85% identical), rat Slc25a45 (85% identical), macaque SLC25A45 (85% identical), guinea pig SLC25A45 (83% identical), dog SLC25A45 (68% identical), tropical clawed frog slc25a45 (55% identical). Paralogues in human: SLC25A48 (48% identical), SLC25A47 (43% identical), SLC25A29 (41% identical), SLC25A20 (35% identical), SLC25A15 (31% identical), SLC25A13 (30% identical), SLC25A2 (30% identical), SLC25A12 (29% identical), SLC25A21 (28% identical), UCP3 (28% identical), SLC25A18 (27% identical), SLC25A22 (27% identical), and 37 more.
Diseases named in the same sentence as SLC25A45 in open-access papers:
SLC25A45 is named in the same sentence as 9 diseases in open-access papers, as found by Europe PMC text mining. Sharing a sentence is not in itself a finding about the gene and the disease. The quoted sentences say what the papers report.
chronic kidney disease (2 papers, 2019 to 2025). Impairment of the renal function secondary to chronic kidney damage persisting for three or more months. "SLC25A45 mutations are associated with chronic kidney disease and preterm birth." (PMID 31612115, 2019).
clear cell carcinoma (1 paper, 2015). "Other genes significantly associated with EOC histological subtypes (p<0.05) included the UGT1A (endometrioid), SLC25A45 (mucinous), SLC39A11 (low malignant potential), and SERPINA7 (clear cell carcinoma)." (PMID 26091520, 2015).
glioma (1 paper, 2019). A benign or malignant brain and spinal cord tumor that arises from glial cells (astrocytes, oligodendrocytes, ependymal cells). "SLC25A45 was downregulated in lower grade glioma (LGG), LUSC, and thyroid carcinoma (THCA)." (PMID 31612115, 2019).
ovarian carcinoma (1 paper, 2015). A malignant neoplasm originating from the surface ovarian epithelium. "SLC25A45 is expressed in skeletal muscle, intestine, brain, and testis and is downregulated during ovarian cancer progression." (PMID 26091520, 2015).
tumor (4 papers, 2019 to 2026). "The downregulated MCOLN3 and SLC25A45 with HR < 1 were considered as tumor suppressors, whereas the upregulated COL17A1, CEP55, KLK10, MET, ITGB6, ANKRD22, and ARNTL2 with HR > 1 were regarded as oncogenes." (PMID 31612115, 2019). "In contrast, MCOLN3 and SLC25A45 were significantly decreased in compare with non-tumor tissues." (PMID 31612115, 2019). "As shown, of the various tumor pathological grades, the expression levels of SLC25A4 (P < 0.01), SLC25A11 (P < 0.0001), SLC25A24 (P < 0.01), SLC25A37 (P < 0.01), SLC25A42 (P < 0.01), SLC25A43 (P < 0.0001), SLC25A44 (P < 0.05) and SLC25A45 (P < 0.05) were significantly different." (PMID 36514121, 2022).
cancer (2 papers, 2019 to 2025). A tumor composed of atypical neoplastic, often pleomorphic cells that invade other tissues. "Metabolic tracing of trimethyllysine in cancer cells demonstrates that SLC25A45 drives the biosynthesis of the key amino acid derivative, carnitine." (PMID 41075794, 2025). "The roles of MCOLN3 and SLC25A45 in cancer are worthy of further investigation." (PMID 31612115, 2019). "The roles of MCOLN3 and SLC25A45 in cancer development have not yet been elucidated." (PMID 31612115, 2019).
SLC25A45 also shares sentences with these, for which no sentence is quoted: pancreatic cancer (4 papers); prostate carcinoma (1); thyroid carcinoma (1).